RN7SL219P (RNA, 7SL, cytoplasmic 219, pseudogene)
Gene: Miscellaneous RNA gene on chromosome 16 (2,013,181 to 2,013,476, forward strand). Ensembl gene ENSG00000265386.
Homologues: Orthologues: chimpanzee Metazoa_SRP (99% identical), macaque Metazoa_SRP (88% identical). Paralogues in human: RN7SL1 (84% identical), RN7SL3 (84% identical), RN7SL2 (83% identical), RN7SL126P (82% identical), RN7SL679P (81% identical), RN7SL296P (81% identical), RN7SL43P (81% identical), RN7SL493P (81% identical), RN7SL566P (81% identical), RN7SL378P (80% identical), RN7SL788P (80% identical), RN7SL186P (80% identical), and 701 more.